MIR6760 (microRNA 6760)
Synonyms: hsa-mir-6760
Gene: MicroRNA gene on chromosome 12 (111,304,142 to 111,304,209, forward strand). Ensembl gene ENSG00000273700.
Homologues: Orthologues: chimpanzee MIR6760 (100% identical).